RHOA (ras homolog family member A)
Diseases named in the same sentence as RHOA in open-access papers (continued):
Sharing a sentence is not in itself a finding about the gene and the disease.
neuroblastoma (35 papers, 2010 to 2025). Neuroblastoma (NB) is the most common solid, extracranial childhood tumor. "We present evidence that single neurodevelopmental disorder-associated missense variants within this loop can enhance GEF2 activity on RhoA and inhibit neurite development in mouse neuroblastoma cells." (PMID 40581118, 2025). "In N1E-115 neuroblastoma cell line, Cdc42 promotes the formation of filopodia and lamellipodia, whereas RhoA causes GC collapse and neurite retraction." (PMID 26379503, 2015). "Pneumolysin has also been reported to cause activation of RhoA and Rac1 GTPases in neuroblastoma cells at sublytic concentrations." (PMID 23527286, 2013). "Attenuation of RhoA activity is required for neurite sprouting formation in Neuro-2A (N2A) neuroblastoma cells following serum withdrawal." (PMID 40581118, 2025). "Exposing human neuroblastoma cells to Aβ was found to increase RhoA activation and subsequent inhibitory CHRM-2 phosphorylation, leading to dystrophic changes in neurite morphology that were reversed by ROCK inhibition using Y27632." (PMID 35563826, 2022). "This suggests a role for TRPM7 in aggressive phenotypes in neuroblastoma cells via p116RIP-mediated RhoA/ROCK regulation and subsequent changes in cytoskeleton dynamics." (PMID 33240883, 2020). "We tested a commercial chemical activator (CN01) and found elevated levels of RhoA-GTP in the neuroblastoma cell line SHSY5Y (arrow)." (PMID 29467497, 2019). "This compound further inhibits the RhoA‐mediated neurite retraction in neuroblastoma cells and analysis of this effect revealed the RhoA‐mediated inhibition of actin depolymerization through the ROCK‐LIM kinase‐cofilin pathway." (PMID 29749605, 2018). "In line with our study, RhoA is required for the activation of a Cl− current by S1P in N1E-115 neuroblastoma cells." (PMID 29479306, 2018). "In neuroblastoma cells, changes in the level of stathmin expression regulate the level of activation of the RhoA/ROCK pathway and consequently modulate changes in microfilaments." (PMID 28977901, 2017). "We found that Cdc42 and RhoA were activated at the leading edge of NG108-15 neuroblastoma cells during spontaneous cycles of protrusion and retraction, respectively." (PMID 26379503, 2015). "Our experiments in the neuronal-like N1E-115 cells demonstrate that recruiting RhoGEF activity to the periphery of these neuroblastoma cells results in localized RhoA activation at the plasma membrane, which is sufficient to induce neurite retraction." (PMID 26435194, 2015). "Addition of Aβ to human neuroblastoma cells resulted in reduced neurite length concomitant with enhanced activation of RhoA and diminished activation of Rac1." (PMID 25339865, 2014). "In neurons, RhoA activation increased neurite retraction and growth cone release while suppression of p160ROCK induced neuronal morphology in N1E-115 neuroblastoma cells." (PMID 23209630, 2012). "Transient expression of RHGF-2 in N1E-115 neuroblastoma cells prevents neurite outgrowth similar to constitutive RhoA activation in these cells." (PMID 22363657, 2012). "The activation of RhoA in in vitro studies has demonstrated neurite retraction in neuroblastoma cell lines and dendritic retraction in brain slices." (PMID 21799943, 2011). "Imaging analysis in N1E-115 neuroblastoma cells revealed that RhoA activity in shaft leads to neurite retraction and that in peripheral domain of growth cones contributes to stabilization of growth cone." (PMID 21904624, 2011). "Furthermore, neuroblastoma cell lines treated with sTREM2 exhibited decreased levels of activated RhoA and elevated levels of inactive RhoA phosphorylated at the Ser188 residue." (PMID 39996845, 2025). "Moreover, Aβ treatment on human neuroblastoma cells led to an increase in RhoA activation and a decrease in Rac1 activation." (PMID 39050707, 2024).
neuroblastoma (continued). "Moreover, reduced stathmin 1 expression in neuroblastoma cells significantly increased the activity of transforming protein RhoA, which is upstream of ROCK, and induced expression of the RhoA/ROCK pathway." (PMID 36230740, 2022). "Moreover, it has also been reported that Unc5a-overexpressing N1E-115 neuroblastoma cells lead to transient Rac1 activation in early stages and RhoA activation in the later stages of neurite outgrowth." (PMID 30934641, 2019). "Previous studies in N1E-115 neuroblastoma cells have demonstrated the requirement of RhoA for the activation of Gα13-mediated chloride conductance by bioactive lipids such as lysophosphatidic acid (LPA) and S1P, and we recently found S1P induced the activation of RhoA in sensory neurons." (PMID 29479306, 2018). "Wnt3a triggers RhoA activity to regulate neurite retraction of mouse neuroblastoma cells." (PMID 28289332, 2017). "In neuroblastoma cells, RhoA activation results in increased phosphorylation of the microtubule associated protein, tau, which could promote its dissociation from microtubules and result in their destabilisation." (PMID 24795148, 2014). "The RhoA sensor was expressed similarly to the various subcellular regions in HEK293 and the neuroblastoma cell line SK-N-SH cells as previously reported for the AKAR4 targeted sensors." (PMID 31399635, 2021). "Work in fibroblasts, rat commissural neurons, and N1E-115 neuroblastoma cells showed that netrin-1/DCC signaling increases Rac1 and Cdc42 activities, while decreasing RhoA activity." (PMID 30934641, 2019). "Similar to our earlier report of small GTPase activation by PLY in human neuroblastoma cells, PLY also activated RhoA and Rac in astrocytes by 4 min after the toxin challenge (not shown)." (PMID 23219469, 2013). "p250GAP is a large, brain-enriched GAP, which hydrolyses RhoA-GTP and Cdc42-GTP and was found to regulate neurite growth in a neuroblastoma and PC12 cell line." (PMID 23226367, 2012). "In SH-SY5Y neuroblastoma models, we show that ANKK1 interacts with the synapse protein FERM ARH/RhoGEF and Pleckstrin Domain 1 (FARP1), which is a guanine nucleotide exchange factor (GEF) of the RhoGTPases RAC1 and RhoA." (PMID 39409035, 2024). "In neuroblastoma, STMN1 phosphorylation was reported to impact on metastasis by altering the levels of tyrosine-protein phosphatase non-receptor type 14 (PTPN14) or in a tubulin-independent manner to enhance transendothelial migration via RhoA/ROCK signaling." (PMID 34771457, 2021). "In this paper, we examine the role of RhoA and Cdc42 in NG108-15 neuroblastoma cells and we show that they are both involved in Sema3A morphological changes with specific spatio-temporal dynamics; we also show that Cdc42 (but not RhoA) exhibits a complex wave behavior." (PMID 26379503, 2015). "Products of other genes, i.e., RHOC, RHOA, CCT5 and TUFM, were reported as also being involved in cytoskeleton rearrangements that are necessary for changes of cell morphology during the neuronal differentiation of neuroblastoma cells." (PMID 20459794, 2010). "Protein expression in these cells showed sensitivity to subtilisin and chymotrypsin similar to that of the adult brain tissue and neuroblastoma cells, with subtilisin at 100nM producing a substantial reduction in neogenin expression but no change of unc-5C or RhoA expression." (PMID 27716118, 2016).
leukemia (32 papers, 2013 to 2026). A malignant (clonal) hematologic disorder, involving hematopoietic stem cells and characterized by the presence of primitive or atypical myeloid or lymphoid cells in the bone marrow and the blood. "One protein, leukemia-associated RhoA guanine exchange factor (LARG), is reported to interact with NIS, but does not affect ion transport and is considered to be a ‘nonpump function’ of NIS." (PMID 32084174, 2020). "The binding of HA to CD44 triggers the signaling of RhoA through the leukemia-associated Rho guanine nucleotide exchange factor (LARG)." (PMID 30676222, 2019). "Nevertheless, RhoA deficiency prevents leukemia development and disease progression in vivo." (PMID 35371049, 2022). "Analysis of RHOA involvement in leukemia and lymphomas from published literature and open source databases shows alteration of RHOA in 1.7% cases mainly by inactivating mutations or deletions while RHOB, RHOC and effector molecules ROCK1 and ROCK2 are not altered." (PMID 35371049, 2022). "Collectively, these studies reveal that Wnt5a induces ROR1 to complex with cortactin/HS1/ARHGEF1 at P841, which induces phosphorylation of cortactin and HS1, activation of ARHGEF1 and RhoA, thereby enhancing leukemia-cell migration." (PMID 30568170, 2019). "Our results provide detailed information on the molecular mechanisms by which MC-3129 induces apoptosis in human leukemia cells (i.e., by activation of RhoA/ROCK1/PTEN and inactivation of PI3K/Akt)." (PMID 29844397, 2018). "The CD44-EGFR complex also associates with leukemia-associated Rho-guanine (LARG) nucleotide exchange factor activating downstream signaling through ras and RhoA." (PMID 23855374, 2013). "Using in vivo functional approaches combined with molecular mechanistic analysis, we identified a reciprocal regulatory loop between B cell lymphoma 6 (Bcl6) and the RhoA-regulated transcriptional complex megakaryoblastic leukemia/serum response factor (MKL/SRF)." (PMID 37967194, 2023). "Mice injected with RhoA-deficient BCR-ABL1 cells did not develop leukemia when compared to mice injected with control cells as evidenced by reduced spleen size and total number of blasts in both spleen and bone marrow." (PMID 35371049, 2022). "Therefore, appropriate systems that could deliver RhoA/RhoC siRNAs to leukemia cells in a safe manner are significant for clinical application in leukemia therapy." (PMID 36674556, 2023). "A leukemia cell study also showed comparable findings, indicating that Wnt5a promoted movement and infiltration via the PI3K/Akt-RhoA pathway." (PMID 40373156, 2025). "The qRT-PCR and ELISA results of this study reflected that the hub genes RHOA, RYK, NLK and MHC-I molecules HLA-A of the atypical Wnt signaling pathway were down-regulated in leukemia cells." (PMID 38962268, 2024). "In leukemia, HOTAIRM1 was considered to be unfavorable and it could activate RHOA/ROCK1 pathway to enhance glucocorticoid resistance by inhibiting ARHGAP18." (PMID 35087800, 2021). "Further study determined that HOTAIRM1 bound to the transcriptional inhibitory region of ARHGAP18 and repressed the expression of ARHGAP18, which led to the increase of RHOA/ROCK1 signaling pathway and promoted GC resistance through antiapoptosis of leukemia cells." (PMID 34262023, 2021). "Our study reveals a novel role for RhoA/ROCK1/PTEN/PI3K/Akt signaling in the regulation of mitochondrial translocation of cofilin and apoptosis and suggests MC-3129 as a potential drug for the treatment of human leukemia." (PMID 29844397, 2018). "However, a study using human leukemia cells showed that activation of the RhoA/ROCK1 pathway decreased p-ERK1/2 in the nucleus, and inhibition of RhoA/ROCK1 led to accumulation of n-p-ERK1/249." (PMID 26148871, 2015).
leukemia (continued). "We show here that under TKI treatment, leukemia stem cells retrieve motility in a reconstituted niche when incubated with SKF96365, a calcium channel inhibitor, and that this effect is dependent on RhoA activation by BCR-ABL independently of its tyrosine kinase activity." (PMID 39199564, 2024).
cervical carcinoma (31 papers, 2010 to 2025). A carcinoma arising from either the exocervical squamous epithelium or the endocervical glandular epithelium. "EGFR, NOTCHI, RHOA and other genes are associated with the lymph node metastasis of cervical cancer." (PMID 31744495, 2019). "On the other hand, it has been described that the overexpression of GTPase RhoA in cervical cancer is associated with distant metastasis after concomitant treatment with chemotherapy and radiotherapy; concordantly, it is known that E6 and E7 oncoproteins regulate the activation of the GTPase RhoA." (PMID 36497200, 2022). "Importantly, these findings raise the interesting possibility that, in the clinic, the combination of chemotherapy using RhoA inhibitors followed by radiotherapy may lead to positive associations, for specific stages of cervical cancers." (PMID 26649141, 2016). "Sevoflurane plays an anti-migration role by inhibiting RhoA and anti-proliferation role by inhibiting Ras, and can also improve the chemotherapy sensitivity of cervical cancer cells." (PMID 40309242, 2025). "Studies have shown that sevoflurane mediates antiproliferation and antimigration of cervical cancer cells by targeting resistance to audiogenic seizures (Ras) and ras homolog family member A (RhoA) and up-regulating miR-203." (PMID 40129947, 2025). "ECT2 and RhoA can be used as potential therapeutic targets for the reversal of tolerance to radiotherapy and chemotherapy for cervical cancer." (PMID 40655948, 2025). "A study confirmed that Ras and RhoA are the targets of sevoflurane in the treatment of cervical cancer and found that sevoflurane can inhibit the downstream signaling pathways Ras/Erk/Akt and Rho/MYPT1/MLC of both targets." (PMID 40309242, 2025). "This suggests that the regulation of RhoA activity affects the sensitivity of cervical cancer cells to radiation therapy." (PMID 40655948, 2025). "Alternative splicing controlled by RNPS1 favors an active Rac1b/RhoA signaling axis, possibly contributing to cervical cancer cell invasion and metastasis." (PMID 37176052, 2023). "This suggests the existence of a FOXO1/RIPOR2/RhoA axis mediated by HPV oncoproteins which is affected in cervical cancer and related to an unfavorable clinical outcome." (PMID 36497200, 2022). "LINC02381 accelerates the metastasis of cervical cancer cells through the regulation of the miR-133b/Ras homolog family member A (RhoA) axis." (PMID 35048795, 2022). "A recent study has shown that miRNA-200b inhibited the proliferation and promoted the apoptosis of cervical cancer cells by directly targeting the Ras homolog family member A (RhoA) gene." (PMID 34944742, 2021). "In cervical cancer, the development of a new treatment protocol based on the presence of RhoA expression is highly expected." (PMID 31976530, 2020). "In conclusion, in this study, we found that the expression of RhoA plays a key role in the prediction of distant metastasis after CCRT in cervical cancer patients." (PMID 31976530, 2020). "From the well-described Rho GTPases, a high RhoA expression was found in vitro and in vivo cervical cancer tissue." (PMID 32443784, 2020). "Currently, there are few reports about the effect of mirna-200b and RhoA protein on the proliferation and apoptosis of cervical cancer cells." (PMID 33336057, 2020). "Small GTPases of the Rho family have been studied mainly on cervical cancer cell lines and RhoA, Rac1, and Cdc42 are the best characterized." (PMID 32443784, 2020). "The expression of RhoA was able to successfully differentiate cervical cancer patients with distant metastasis after CCRT." (PMID 31976530, 2020). "Our study is the first to demonstrate that the expression of RhoA is closely related to distant metastasis after CCRT in advanced-stage cervical cancer." (PMID 31976530, 2020). "miRNA-200b can inhibit the proliferation and promote the apoptosis of cervical cancer cells by targeting the RhoA gene." (PMID 33336057, 2020).
cervical carcinoma (continued). "In this study, HeLa cells of human cervical cancer were taken, and bioinformatics software was adopted to verify the target relationship between miRNA-200b and RhoA." (PMID 33336057, 2020). "This article aims to investigate the effect of miRNA-200b on the proliferation and apoptosis of cervical cancer cells by targeting RhoA." (PMID 33336057, 2020). "Since it is established that RhoA is associated with cervical cancer metastasis, the TGF-β-RhoA signaling pathway must also play an important role in the regulation of metastasis of cervical cancer cells." (PMID 31546735, 2019). "The expression level of Rac1 and RhoA were found to be increased in several cancers including cervical cancer." (PMID 31870092, 2019). "ROCK2, an important signaling molecule, can promote cervical cancer metastasis by upregulating and activating the expression and function of moesin protein through RhoA/ROCK2 pathway." (PMID 24992025, 2014). "In this study we analyzed the expression of the GTPases Rac1, RhoA, Cdc42, and the Rho-GEFs, Tiam1 and beta-Pix, in cervical pre-malignant lesions and cervical cancer cell lines." (PMID 22443139, 2012). "In this study, we investigated the effects of VEGF-C on actin cytoskeleton remodeling and on cervical cancer cell migration and invasion and how the actin-regulatory protein, moesin regulated these effects through RhoA/ROCK-2 signaling pathway." (PMID 20429915, 2010). "Taken together, we demonstrated that VEGF-C activated RhoA/ROCK-2/moesin cascade in cervical cancer cells, leading to the accelerated cancer cell migration and invasion." (PMID 20429915, 2010). "Moreover, RhoA promoted epidermal stem cell proliferation, and overexpression of RhoA stimulated proliferation of cervical cancer cells." (PMID 40943293, 2025). "Finally, this workflow was repeated to generate HeLa (human female cervical carcinoma with 82 modal chromosomes; hypertriploid) cell lines expressing mNeonGreen-tagged anillin, Ect2 and RhoA." (PMID 36416720, 2022). "In our study, RacGAP1 could increase the level of active RhoA, which in turn caused changes in the downstream effector ROCK1 in cervical cancer." (PMID 35831303, 2022). "We found that RhoA expression is correlated with cervical cancer metastasis." (PMID 31976530, 2020). "However, there have been few reports on the effects of miRNA-200b and RhoA proteins on the proliferation and apoptosis of cervical cancer cells." (PMID 33336057, 2020). "In summary, miRNA-200b can inhibit the proliferation and promote the apoptosis of HeLa cells through the targeted regulation of RhoA; its mechanism of action may be that miRNA-200b inhibits the immune escape of cervical cancer cells." (PMID 33336057, 2020). "It is suggested that miRNA-200b inhibits the proliferation ability and promotes the apoptosis of HeLa cells by targeting RhoA and may inhibit the development of cervical cancer by inhibiting the immune escape of cervical cancer cells." (PMID 33336057, 2020). "Contextually, a combination of chemotherapy containing RhoA inhibitors and radiotherapy might be relevant for various stages of cervical cancer development." (PMID 32443784, 2020). "In addition to the evidence for correlations between CA9 and RHOA functions, CA9 has also been found to promote cervical cancer cell invasions by inhibiting RHOA in vitro." (PMID 30034621, 2018). "Although additional molecular studies are needed, RhoA represents a potential target for UV radiation-induced carcinogenesis in skin, as well as for gamma radiation-induced damage in cervix carcinomas, where RhoA was also shown to mediate double-strand breaks repair." (PMID 26823948, 2016). "Moreover, the higher expression of RhoA could play an important role in the prediction of distant metastasis after concurrent chemoradiotherapy in bioptic samples obtained from 49 cervical cancer patients suggested the key role of RhoA as a prognostic marker." (PMID 32443784, 2020).